RN7SL856P (RNA, 7SL, cytoplasmic 856, pseudogene)
Gene: Miscellaneous RNA gene on chromosome 2 (25,058,032 to 25,058,329, forward strand). Ensembl gene ENSG00000276653.
Homologues: Orthologues: chimpanzee Metazoa_SRP (99% identical), macaque Metazoa_SRP (96% identical). Paralogues in human: RN7SL1 (85% identical), RN7SL2 (85% identical), RN7SL3 (84% identical), RN7SL230P (82% identical), RN7SL650P (82% identical), RN7SL448P (81% identical), RN7SL655P (81% identical), RN7SL126P (81% identical), RN7SL130P (81% identical), RN7SL218P (81% identical), RN7SL296P (81% identical), RN7SL357P (81% identical), and 702 more.